CCND1 (cyclin D1)
Diseases named in the same sentence as CCND1 in open-access papers (continued):
Sharing a sentence is not in itself a finding about the gene and the disease.
acute myeloid leukemia (17 papers, 2010 to 2025). Acute myeloid leukemia (AML) is a group of neoplasms arising from precursor cells committed to the myeloid cell-line differentiation. "In PTEN deficient acute myeloid leukemia (AML) mice, a high number of cyclin D1-expressing cells populated the bone marrow." (PMID 31366089, 2019). "NUP98-NSD1 transformed cells were highly enriched for the gene sets acute myeloid leukemia, hematopoietic cell lineage, and Cyclin D1 when compared to NRASG12D cells." (PMID 32993115, 2020). "In acute myeloid leukemia (AML), metformin induces G0/G1 arrest mediated by p21/p27 and reduces levels of cyclin-dependent kinase (CDK) 4 and cyclin D1." (PMID 41050082, 2025). "Furthermore, the CXCR4 antagonist induces the apoptosis of acute myeloid leukemia (AML) cells, and this apoptosis is mediated by the upregulation of miR-15a/miR-16-1, which results in the downregulation of the target genes cyclin D1 and Bcl-2." (PMID 35941537, 2022). "For example, in acute myeloid leukemia (AML), GSK3α but not GSK3β suppresses c-myc and cyclin D1 to maintain stemness." (PMID 41300341, 2025).
asthma (17 papers, 2009 to 2025). "We found that CCND1 upregulation in alveolar lavage fluid was positively associated with asthma severity." (PMID 40160461, 2025). "CCND1 and IL-6R have been reported to be associated with asthma inflammation and high serum IgE in patients." (PMID 38380329, 2024). "Moreover, an association of the CCND1 genotype with the asthma susceptibility has been observed." (PMID 36264868, 2022). "Cyclin D1 (CCND1), a unique hub gene for DEHP action in asthma, is associated with the rest of the cell cycle, and its upregulation would further increase potentially exacerbate airway wall thickening and airway remodelling." (PMID 40160461, 2025). "Cyclin D1 (CCND1) is a crucial regulator for cell proliferation and has been found to be upregulated in the airway smooth muscle of individuals with asthma, as well as being associated with airway remodeling in animal models." (PMID 38279356, 2024). "CCND1 is closely correlated with the development of asthma; in particular, CCND1 rs9344 is considered an early detection marker for asthma." (PMID 39769348, 2024). "As regarding the role of cyclin D1 (CCND1), an essential cell cycle control gene, convictive literature has revealed that CCND1 is closely correlated to the development of asthma." (PMID 36992945, 2023). "Moreover, we found that a important element cyclin D1 (CCND1) up-regulated in the asthma cellular model (PDGF-induced ASMCs)." (PMID 36992945, 2023). "Collectively, these findings reveal a YTHDF1/cyclin D1 axis in asthma." (PMID 36992945, 2023). "Mechanistically, YTHDF1 significantly combined with cyclin D1 mRNA, thereby enhancing its mRNA stability through m6A-depedent pattern, which may provide novel therapeutic strategy for asthma." (PMID 36992945, 2023). "Collectively, these findings reveal a novel axis of YTHDF1/m6A/cyclin D1 in asthma’s airway remodeling, which may provide novel therapeutic strategy for asthma." (PMID 36992945, 2023). "However, based on our analysis, its target gene, cyclin D1 (CCND1) is upregulated in asthma serum-sensitized human airway smooth muscle." (PMID 36264868, 2022). "Cyclin D-1 gene (CCND1), another regulator of the Wnt/β-catenin signaling pathway, is differentially methylated after exposure to HCA and associated with airway remodeling and smooth muscle proliferation in asthma." (PMID 32850550, 2020). "In a human asthma lung tissue model, the YTHDF1 gene binds to the cyclin 1 (CCND1) mRNA modification site, thereby stimulating the proliferation and migration of airway smooth muscle cells, which are involved in airway spasm and contraction during asthma pathogenesis." (PMID 39108751, 2024). "Notably, three common target genes—cyclin D1 (CCND1), vascular endothelial growth factor A (VEGFA), and glycogen synthase kinase-3 beta (GSK3B)—were identified as being regulated by all three miRNAs within pathways associated with asthma and inflammation." (PMID 38279356, 2024). "Overall, we could conclude that cyclin D1 (CCND1) significantly participate in the asthma." (PMID 36992945, 2023). "PTGS2, IL10, CTSB, JAK2, and MTOR were significantly downregulated in alveolar lavage fluid with increasing asthma severity, while MMP9, GSK3B, BCL2, EGFR, and CCND1 were upregulated." (PMID 40160461, 2025). "The m6A-dependent modulation of CCND1 by YTHDF1 provides a new mechanism in asthma etiology, suggesting possible treatment approaches aimed at the YTHDF1-CCND1 axis." (PMID 41008562, 2025). "In this study, we constructed the PPI network; IL6, CASP3, EGFR, MAPK8, ESR1, CCND1, and PPARG were found to be the core genes of YPF in treating asthma." (PMID 36105239, 2022).
asthma (continued). "Moreover, we found cyclin D1 (CCND1), an essential cell cycle control gene closely correlated to the development of asthma, was up-regulated in the PDGF-induced ASMCs." (PMID 36992945, 2023). "However, the expression of CCND1 is markedly reduced in the bronchial epithelial cells of individuals with asthma in comparison to those without the condition." (PMID 40160461, 2025). "Our study suggests that activation of AMPK modulates miR-206/HDAC4/cyclin D1 signaling pathway, particularly targeting on HDAC4, to suppress ASMCs proliferation and therefore has a potential value in the prevention and treatment of asthma by alleviating airway remodeling." (PMID 29483552, 2018).
astrocytoma (17 papers, 2011 to 2023). "High expression of Cyclin D1 is associated with the pathological grade and proliferative activity of astrocytomas." (PMID 37830634, 2023). "In our study, we discovered that knockdown of galectin-3 attenuated cell proliferation, migration, and invasion and inhibited the Ki-67, VEGF, and cyclin D1 protein expression in astrocytoma cells." (PMID 37185758, 2023). "On the other hand, it is well known that cyclin D1 is often overexpressed in astrocytomas, as well as other malignant neoplasms, as seen in our astrocytoma cell line." (PMID 34830034, 2021). "Our observations of the fukutin knockdown-driven decreases in cell proliferation ability and cyclin D1 expression level in 1321N1 cells highlight that fukutin enables astrocytoma cells to proliferate." (PMID 34830034, 2021). "Significant differences were observed in the relative expression of Bmi-1 and CCND1 between grades II and IV astrocytomas (p<0.001 for both), with a 1.15-fold and 1.31-fold increase in their expression in GBM samples, respectively." (PMID 26317630, 2015). "Ki-67 and cyclin D1 are malignant biomarkers of astrocytoma." (PMID 37185758, 2023). "Many other studies showed that the overexpression of cyclin d1 occurs in high-grade astrocytoma." (PMID 35223330, 2022). "In addition, Fli-1 silencing inhibited proliferation, migration, and invasion and led to the downregulation of Ki-67, VEGF, and cyclin D1 expression in the astrocytoma cells." (PMID 28418872, 2017). "Ki-67 and cyclin D1 are markers of astrocytoma malignancy, and VEGF is a marker of angiogenesis." (PMID 28418872, 2017). "In vitro studies indicate that progesterone promotes cell proliferation in astrocytomas, as well as the expression of genes that are important for tumor growth and dissemination, e.g., cyclin D1, epidermal growth factor receptor (EGFR) and vascular endothelial growth factor (VEGF) 35,36." (PMID 27626480, 2016). "NUSAP1 also upregulated the expression of the downstream targets of HH pathway including PTCH1, HIP1, CCND1, CCNE1 and HDAC1 in astrocytoma." (PMID 28899410, 2017). "Fli-1 knockdown attenuated the proliferation, migration, and invasion of astrocytoma cells and downregulated the expression of Ki-67, VEGF, and cyclin D1." (PMID 28418872, 2017). "In our study, we found that knockdown of GSK3B attenuated cell proliferation, migration, and invasion and inhibited the β-catenin, p-GSK3B ser9, VEGF, and Ki-67 but not cyclin D1 protein expression in astrocytoma cells." (PMID 37185758, 2023). "Of the 25 samples diagnosed with grade II tumors, one sample belonged to the Gemistocytic Astrocytoma subtype with a negative expression of cyclin D1." (PMID 31583003, 2019). "We also demonstrate a potential prognostic value for Cyclin D1 overexpression which appears correlated to EFS and to a lesser degree to OS in our series; this has been previously reported for astrocytomas but never reported to our knowledge for OGs." (PMID 29489901, 2018). "As for 4E‐BP1, eIF4E, and cyclin D1, expression in gliosis was significantly lower than in high‐grade DIA but not grade II astrocytoma." (PMID 27440383, 2016).
clear cell renal cell carcinoma (17 papers, 2014 to 2025). "Under the context of clear cell renal cell carcinoma, nuclear transcription factor Y binds directly to the promoter region of CCND1, thus transactivating its expression." (PMID 35246017, 2022). "For example, TTN-AS1 regulates the TTN-AS1/miR-195/cyclin D1 axis through sponge adsorption so as to promote tumor cell proliferation and modulate tumor cell cycle activities in clear cell renal cell carcinoma." (PMID 34671381, 2021). "In this study, we focused on the role of CCND1 in the clinical outcome of clear cell renal cell carcinoma (ccRCC)." (PMID 31183974, 2019). "In addition, clear cell renal cell carcinoma (ccRCC) reveals low CCND1 correlates with adverse outcomes and suggests a unique prognostic role in ccRCC." (PMID 39188436, 2024). "In renal clear cell carcinoma, ISG20 positively regulates the expression of CCND1, which promotes cell proliferation and upregulates the expression of MMP9, which is involved in the breakdown of the extracellular matrix and promotes metastasis." (PMID 39428941, 2025). "In clear cell renal cell carcinoma, transcription factor NFYA was reported to be able to simultaneous transactivating CCND1 and CDK4 to promote G1/S cycle transition thus accelerating tumor development and predicting poor prognosis." (PMID 35365622, 2022). "After treatment of clear cell renal cell carcinoma cells with LGK974, the expression levels of β-catenin, cyclin D1, c-Myc, MMP9, and MMP2 were significantly decreased." (PMID 33923996, 2021). "Alternatively, COPS3 may promote clear cell renal cell carcinoma progression by regulating phospho-AKT (Thr308), Cyclin D1, and Caspase-3 expression, while COPS5, -6, and -8 overexpression enhanced cellular proliferation, EMT, and vascular invasion." (PMID 38466642, 2024). "This may act to counter the proliferative effects of MYC, cyclin D1 and MDM2; however, and concerningly, CDKN1A is also overexpressed in clear-cell renal cell carcinoma relative to normal kidney." (PMID 24827579, 2014). "In addition, the overexpression of COPS3 could contribute to the progression of clear cell renal cell carcinoma (ccRCC) via regulation of phospho-AKT, Cyclin D1, and Caspase-3." (PMID 35903293, 2022). "Therefore, the hub gene CCND1 and PECAM1/CD31 may play key role in the progression of clear cell renal cell carcinoma." (PMID 31850854, 2019).
colitis (17 papers, 2011 to 2026). Inflammation of the colon. "As a consequence, TNF-α induces the β-catenin target gene expressions including PCNA, Cyclin D1 and c-Myc, thus promoting the colitis-associated tumor development." (PMID 26910375, 2016). "Interestingly, RIPK3-deficient mice had increased Wnt-β-catenin signaling shown by induction of genes important for IEC survival, proliferation and invasiveness (cMyc, Cox2 and Wisp1), and cell cycle progression (Cyclin B1, Cyclin D1, Cyclin E and p21) during colitis-associated CRC." (PMID 27344176, 2016). "In light of the observed upregulation of β-catenin and cyclin D1 in PDCOs and colitis-affected mouse colon tissues, we investigated how MDEs influence these proteins in a cancer context." (PMID 39769282, 2024). "It has been reported that SLC3A2 regulates the expression of cyclin D1 in IECs to participate in mouse colitis." (PMID 39688910, 2024). "Similarly, genes involved in proliferation and differentiation (e.g., Cyclin D1, p21), pro-apoptosis (e.g., Bax, Bak, caspase-3), and inflammation (e.g., iNOS, IL-6); previously shown to be regulated by VitD, were altered in HF-fed mice with colitis/CAC." (PMID 36768196, 2023). "Similar to the Apcmin/+mouse model, the expression levels of pSTAT3, Cyclin D1 and C-myc were greatly elevated in the Mlkl-/-→Mlkl-/- and WT→Mlkl-/- intestinal polyps compared with the Mlkl-/-→WT and WT→WT intestinal polyps at day 80 of the AOM/DSS-induced colitis-associated tumorigenesis." (PMID 33767595, 2021). "TF2A administration increased protein levels of YB-1 and CCND1 and mRNA levels of E2F target genes in colon tissues, indicating a potential role of TF2A in alleviating colitis." (PMID 35143419, 2022). "Once activated, both β-catenin and NF-kB transactivate many common target genes such as Ptges2, Nos2 and Ccnd1 and respective protein levels [COX2, inducible-NOS (iNOS) and Cyclin D1] with established roles in the development of colitis and CAC." (PMID 36584137, 2022). "We observed that DSS increases the expression of STAT3-related proteins, i.e. Cdk4 and cyclin D1, whereas RA inhibits these increases in the colons of mice with DSS-induced colitis." (PMID 28383063, 2017). "We noticed that cyclin D1 was overexpressed together with COX-2 and another inflammatory enzyme iNOS in DSS-induced colitis, and this was suppressed by PE administration." (PMID 28848431, 2017). "Previous work revealed that cold exposure alleviates colitis in mice; this study extends that finding by demonstrating that cold exposure enhances intestinal regeneration even in healthy mice, upregulating proliferation markers (Mki67, PCNA, Cyclin D1)." (PMID 41898256, 2026). "During colitis, however, we hypothesize that pathological changes in matrix elasticity within the colon promote formation of FAK-integrin complexes, cyclin D1 upregulation and progression through the cell cycle." (PMID 21887232, 2011).
MALT lymphoma (17 papers, 2011 to 2026). An indolent, extranodal type of non-Hodgkin lymphoma composed of small B-lymphocytes (centrocyte-like cells). "MALT lymphoma cells immunohistochemically exhibit CD20+, CD79a+, CD5-, CD10-, CD23-, CD43+/-, and cyclin D1-." (PMID 36614921, 2022). "Typically, MALT lymphoma shows positivity for CD19, CD20, CD22, and CD79a, and negativity for CD3, CD5, CD10, CD23, BCL6, and cyclin D1." (PMID 33499258, 2021). "Tumours analyzed were CD20+, cyclin D1−, CD23−, CD5−, Bcl-6−, CD43−, and CD10−, supporting the diagnosis of MALT lymphoma." (PMID 23420489, 2013). "Typically, neoplastic MALT lymphoma cells express markers of B-cell lineage, and are negative for cyclin D1, CD23, CD10 and CD5, with rare exceptions." (PMID 23425357, 2013). "MCL cells coexpress CD20, CD5, and cyclin D1, unlike MALT lymphoma." (PMID 33499258, 2021). "Immunophenotype can be determined either by immunohistochemistry or by flow cytometry, and MALT lymphomas are usually positive for CD19/20/22/79 and negative for CD5/10/23/BCL-6 and cyclin D1." (PMID 32908756, 2020). "Furthermore, MALT lymphomas distinctively express CD21 and are negative for CD5, CD10, and cyclin D1, along with a low Ki-67 proliferation index." (PMID 39411128, 2024). "MALT lymphomas are typically negative for CD5, CD10, BCL6 and cyclin D1." (PMID 34814897, 2021).
metastatic melanoma (17 papers, 2010 to 2025). A melanoma that has spread from its primary site to another anatomic site. "Aberrant regulation of the CDK4/6-cyclin D1 axis is associated with the development of metastatic melanoma and breast cancer." (PMID 35190631, 2022). "The increased expression of cyclin D1 in both primary and metastatic melanoma indicates its crucial role in tumor progression." (PMID 38339136, 2024). "We have previously demonstrated that inactivation of Fbxo4 in the BrafV600ECA/+ background triggers cyclin D1-dependent, metastatic melanoma." (PMID 27977682, 2016). "In many studies, expression of cyclin D1 is enhanced in primary and metastatic melanoma." (PMID 29214525, 2017). "While the expression levels of cyclin D1 increase from benign to malignant, in metastatic melanomas the expression level decreases which in turn demonstrated by the clustering method clearly delineating multiple subgroups of samples in the presumably homogenous metastatic melanoma cohort." (PMID 20642836, 2010). "Herein, this study investigated the efficacy of ArcA, a potent inhibitor of the cyclin D1/CDK4 complex, in metastatic melanoma cells." (PMID 39948552, 2025). "In this study, we evaluated the efficacy of arcyriaflavin A (ArcA), a potent inhibitor of the cyclin D1/CDK4 complex, in suppressing aggressive phenotypes of metastatic melanoma." (PMID 39948552, 2025). "In human metastatic melanoma cell lines, PRMT5 was predominantly cytoplasmic, and associated with its enzymatic cofactor Mep50, but not STAT3 or cyclin D1." (PMID 24098663, 2013).